PELI1 (pellino E3 ubiquitin protein ligase 1)
Diseases named in the same sentence as PELI1 in open-access papers (continued):
Sharing a sentence is not in itself a finding about the gene and the disease.
tumor (continued). "Similarly, considerable reduce of MDA-MB-231 cells-derived tumor nodules in lung were also detected in mice with both PELI1 knockdown and EGFR inhibition, as further confirmed by the decreased GFP fluorescence intensity indicating the MDA-MB-231 cells number in lung." (PMID 36841821, 2023). "However, a recent study reported that PELI1 could promote radiotherapy sensitivity by inhibiting noncanonical NF-κB in esophageal squamous cancer, suggesting that PELI1 was a tumor suppressor." (PMID 34991623, 2022). "Moreover, we found PELI1‐mediated IR‐induced tumor cell apoptosis in vivo and in vitro." (PMID 34738714, 2022). "The inhibition of Peli1 in papillary thyroid cancer (PTC) cells induces downregulation of the PI3K-AKT pathway and leads to suppression of tumor growth, proliferation, and migration." (PMID 37176148, 2023). "The results revealed that knockdown of NIK, the master protein kinase of the noncanonical NF‐κB signaling pathway, significantly restored the decreased IR‐induced apoptosis in PELI1‐knockdown TE‐1 and ECA‐109 tumor cells." (PMID 34738714, 2022). "We performed a western blot analysis of the relative expression of PELI1 and p-AKT in the mice tumor and found that PELI1 and levels of p-AKT were decreased in miR-30c-5p-EV-treated tumors compared with NC-EV-treated tumors." (PMID 34991623, 2022). "In addition, miR-21 was reported to the regulate tumor suppressor and regulator of B-cell differentiation BTG2 and E3 ubiquitin ligase PELI1 which are known to regulate c-REL levels." (PMID 38539461, 2024). "In contrast, TAM (tumor‐associated macrophage) C16 was enriched in lung tumors and highly expressed PDE4B but not IL1B, MDM2, or PELI1." (PMID 38010945, 2024). "In addition, PELI1 knockdown significantly inhibited IR‐induced activation of apoptotic signaling pathways in TE‐1 and ECA‐109 tumor cells, which was reflected by the inhibition of the cleavage of caspase 9, caspase 7, caspase 3, and PARP." (PMID 34738714, 2022). "Moreover, we found that the expression of miR-30c-5p was inversely correlated with PELI1 in PTC samples and further confirmed that miR-30c-5p was a tumor-suppressive miRNA that directly targeted PELI1 to inhibit PTC cell proliferation and migration." (PMID 34991623, 2022). "In addition, factors inducing inflammatory responses, like Peli1, Pgts2, Socs3, and Tnfrsf9, were downregulated, while an inhibitor of the NF-κB pathway (Nfkbie) was upregulated in HIF-1α-KD tumor cells." (PMID 33142239, 2020). "It was demonstrated that tumor volume and weight were significantly decreased after administration of miR-30c-5p-carrying-hUC-MSC-EV compared to the control group, which could be due to the inhibition of E3 ubiquitin ligase Pellino-1 (PELI1) by miR-30c-5p." (PMID 35955703, 2022). "Mechanistic studies have suggested that PELI1 functions as an essential mediator of IR‐induced tumor cell apoptosis by suppressing noncanonical NF‐κB signaling, leading to inhibition of the anti‐apoptotic protein Bcl‐XL and induction of the apoptotic signaling pathway during radiotherapy." (PMID 34738714, 2022). "In concert with the pattern of PELI1‐modulated noncanonical NF‐κB signaling, knockdown of PELI1, which enhanced IR‐induced noncanonical NF‐κB signaling, significantly promoted the transcription of the anti‐apoptotic gene Bclx1 in IR‐treated TE‐1 tumor cells." (PMID 34738714, 2022). "Overall, these data provided strong evidence that engineered hUCMSC-EVs delivering miR-30c-5p could effectively inhibit PELI1 expression and tumor progression in PTC, which partly promoted the clinical transformation of miR-30c-5p-PELI1 axis in tumor treatment." (PMID 34991623, 2022). "However, the overexpression of PELI1, which impaired IR‐induced noncanonical NF‐κB signaling, dramatically inhibited the transcription of this gene in tumor cells." (PMID 34738714, 2022).
tumor (continued). "Therefore, we speculated that PELI1 may also regulate IR‐induced apoptosis through regulating the noncanonical NF‐κB signaling in tumor cells." (PMID 34738714, 2022). "Since IR‐induced noncanonical NF‐κB inhibits tumor cell apoptosis and PELI1 negatively regulates IR‐induced activation of this signaling pathway, we speculated that PELI1 may affect IR‐induced apoptosis of tumor cells through modulation of noncanonical NF‐κB signaling." (PMID 34738714, 2022). "As a consequence, PELI1 inhibited the noncanonical NF‐κB–induced expression of the anti‐apoptotic gene BCL2 like 1 (Bclxl; also known as BCL2L1), leading to an enhancement of the IR‐induced apoptosis signaling pathway and ultimately promoting IR‐induced apoptosis in tumor cells." (PMID 34738714, 2022).
cancer (15 papers, 2017 to 2025). A tumor composed of atypical neoplastic, often pleomorphic cells that invade other tissues. "This pan-cancer study revealed the diagnostic, prognostic and immunomodulatory potential, along with the biological function and mechanism of PELI1, supporting its role as a promising therapeutic target in LIHC." (PMID 41562077, 2025). "Our systematic pan-cancer analysis reveals the diagnostic, prognostic, and oncogenic roles of PELI1, with in depth mechanism verification in LIHC, nominating it as a promising therapeutic target in LIHC." (PMID 41562077, 2025). "PELI1, an E3 ubiquitin ligase, has been implicated in the pro-cancer progression of various malignant tumours." (PMID 38528516, 2024). "Currently, although the involvement of the Pellino E3 Ubiquitin Protein Ligase 1 (PELI1) in the human growth of some malignant tumors has been demonstrated, its association with PC remains uncertain." (PMID 38528516, 2024). "Taken together, these data demonstrated that PELI1 mediated EGFR stability through K63-linked ubiquitination to be involved in the aberrant EGFR signaling in cancers." (PMID 36841821, 2023). "The molecular mechanism underlying the high expression and oncogenic roles of PELI1 in cancers remains limited." (PMID 36841821, 2023). "As recent studies underline that Peli1 also interplays between cancer metabolism and DNA damage, the exact roles of Peli1 in metabolic reprogramming, DNA repair process, and their link are worth further studied and analyzed as an effective therapeutic target for cancers." (PMID 37176148, 2023). "However, the molecular mechanism underlying the high expression and oncogenic roles of PELI1 in cancers remains limited." (PMID 36841821, 2023). "A systematic investigation of PELI1—including its expression profiles, clinical significance, immune correlations, and underlying molecular mechanisms—could provide novel mechanistic insights into tumorigenesis and facilitate the development of innovative cancer therapies." (PMID 41562077, 2025). "The E3 ubiquitin ligase Pellino1 (PELI1) is ubiquitously expressed in human tissues and primarily modulates inflammatory and immune responses; however, its pan-cancer biological significance remains poorly characterized." (PMID 41562077, 2025). "To evaluate the prognostic significance of PELI1, we correlated its expression with clinical outcomes across different cancers." (PMID 41562077, 2025). "Compared with normal samples, PELI1 methylation levels showed significant differences in 11 cancer types." (PMID 41562077, 2025). "IHC analysis of 90 paraffin-embedded PC and paracancerous tissues revealed a substantially greater positive rate of PELI1 in cancer tissues than in matching paracancerous tissues." (PMID 38528516, 2024). "Despite PELI1’s well-established cancer-promoting role in solid tumors, its exploration in PC remains uncharted." (PMID 38528516, 2024). "PELI1 is known to play an important role in inflammation and autoimmunity,and also been found to play a pro-cancer role in malignant tumors." (PMID 38528516, 2024). "Considering the impact of deregulated DNA damage repair in cancer development and progression, the novel role of Peli1 in regulating DNA damage repair becomes more remarkable." (PMID 37176148, 2023). "Understanding Peli1 functions holds promise for developing targeted cancer therapies and improving clinical management." (PMID 38179042, 2023). "Peli1 is critical in the development and progression of various diseases, particularly immune-related disorders and cancers." (PMID 38179042, 2023). "This review will advance future research on the role of Peli1 in immune diseases, cancers, and other conditions." (PMID 38179042, 2023). "The rate of PELI1 high expression was 56.5% (187/331) in ESCC cancer tissues, which was significantly lower than the 96.1% in matched cancer–adjacent normal tissues (318/331, P < 0.001)." (PMID 34738714, 2022).
cancer (continued). "The aberrant expression of E3 ubiquitin ligase Pellino-1 (PELI1) contributes to several human cancer development and progression." (PMID 34991623, 2022). "By addressing these gaps, our work will pave the way for precise PELI1-targeted cancer therapies." (PMID 41562077, 2025). "Such functional divergence may reflect tissue-specific signaling contexts, highlighting the complexity of PELI1 in cancer biology." (PMID 41562077, 2025). "PELI1 may drives cancer progression through epigenetic regulation involving DNA methylation and N6-methyladenosine (m6A) RNA modifications." (PMID 41562077, 2025). "Drawing from this background, we posit a potential pro-cancer role for PELI1 in PC." (PMID 38528516, 2024). "Pellino-1 (PELI1), a novel cancer-related E3 ubiquitin ligase, is expressed in various cancers." (PMID 39187514, 2024). "Based on the commonly high-expression of PELI1 in cancers, the co-inhibition of the PELI1-EGFR may also repress the metastasis in other cancers." (PMID 36841821, 2023). "Therefore, it is likely that the forced activation of receptor downstream signalling cascade by Peli1 expression leads to severe impairment of the mitotic spindle checkpoint, thus contributing to production of chromosome aneuploidy and cancer." (PMID 28410192, 2017). "However, a comprehensive pan-cancer characterization of PELI1 remains unexplored." (PMID 41562077, 2025). "PELI1 could potentially serve as a novel biomarker for diagnosing different cancer types." (PMID 41562077, 2025). "Moreover, since modulating DNA repair is considered an efficient strategy to sensitize cancer cells to radiotherapy, the regulation of Peli1 expression or activity may be an attractive therapeutic approach." (PMID 37176148, 2023). "Thus, we further examined the contributions of PELI1 to aberrant EGFR signaling in cancers." (PMID 36841821, 2023). "Interestingly, the role of Peli1 in cancer and cancer metabolism has been well established." (PMID 37176148, 2023). "KEGG enrichment analysis further highlighted PELI1-mediated pathways, including PI3K-AKT, MAPK, Wnt and TNF signaling—pathways well-characterized in LIHC for targeted anti-cancer drug development." (PMID 41562077, 2025). "Recently, the crucial role of Peli1 in regulating phosphatidylinositol-3-kinase (PI3K)-AKT signaling, the major effector pathway that reprograms cellular metabolism in cancer, has been revealed." (PMID 37176148, 2023). "As expected, Gefitinib, an inhibitor of EGFR approved for the clinical treatment of cancers, induced a dose-dependent reduction of the cell viability in MDA-MB-231 cells, and this is attenuated by the enforced expression of PELI1." (PMID 36841821, 2023). "we found that combination of PELI1 knockdown and EGFR inhibition significantly decreased metastatic potential of cancer cells to lung in caudal vein xenograft models compared to the either single treatment, as demonstrated by reduced number of micrometastatic nodules." (PMID 36841821, 2023). "Peli1 activates the AKT pathway and is involved in various biological and pathological processes, including cancer progression, drug resistance, angiogenesis, T follicular helper (Tfh) cell differentiation, microglia activation, glycolysis, and macrophage M1 polarization." (PMID 38179042, 2023). "Given that Peli1 expression is exceedingly suppressed under non-pathological conditions, while it is activated and upregulated in diseases such as cancer, it is widely accepted that regulating Peli1 could be a highly advantageous strategy in cancer treatments." (PMID 37176148, 2023).
infection (11 papers, 2013 to 2025). The state of being infected such as from the introduction of a foreign agent such as serum, vaccine, antigenic substance or organism. "Peli1−/− animals recruit significantly more neutrophils to the airway following NTHi infection which is associated with an increase in the neutrophil chemokine, KC, in bronchoalveolar lavage fluid as well as enhanced clearance of NTHi from the lung." (PMID 31417543, 2019). "Peli1 exerts pathogenic effects on central nervous system (CNS) antiviral infections." (PMID 38179042, 2023). "We believe that the role of Peli1 and the inflammatory response observed depends entirely on the type of infection." (PMID 37296648, 2023). "The role of Peli1 in infection depens on the infection type, which is common in studies on the role of other E3 ligases in infectious diseases." (PMID 38179042, 2023). "Within the ubiquitin pathway, E3 ubiquitin ligases including HOIP (RNF31), TRAF2, and Pellino (PELI1) showed marked infection-dependent changes at the level of phosphorylation (e.g. RNF31_S445) and ubiquitination (e.g. PELI_K202 early, TRAF2_K313 late)." (PMID 34085925, 2021). "We next performed siRNA knockdown to reduce Peli1 expression by 41% in HTR8 cells followed by infection with the clinical Asian-lineage FSS13025 strain (ZIKV-FSS13025)." (PMID 32544190, 2020). "We found that Peli1 expression was significantly enhanced on HTR8 cells at day 6 post infection (pi)." (PMID 32544190, 2020). "A population of IFNγ positive innate CD19+ B cells were transiently recruited to the airways at day 2 post-infection, and this was significantly increased in Peli1−/− animals." (PMID 32984077, 2020). "To establish a role for Pellino-1 in lung inflammation and infection, we adopted a murine model of COPD in Pellino-1 (Peli1−/−) knockout mice and WT littermates." (PMID 31417543, 2019). "Infection with NH/P68 also caused down-regulation of IFNAR1 and NLRP3 receptors, MYD88 adaptor proteins, as well as other molecules involved in modulating receptor signaling pathways (JUN, PELI1, TBK1, and TICAM2)." (PMID 40530033, 2025). "Thus, in infectious diseases, the differential targeting of Peli1 according to differences in its regulatory functions provides new pathways for treating infections." (PMID 38179042, 2023). "Inhibiting Peli1 improves bacterial clearance during NTHi infection." (PMID 38179042, 2023). "Peli1 enhances T cell recruitment to the infection by increasing Gpr156 expression." (PMID 38179042, 2023). "We saw an increase in early tissue injury, with increased leakage of IgM and total protein into the BALF of Peli1−/− animals at 96 h post-infection, although histological examination of the lung over 8 days showed similar progressive injury to the bronchial and bronchiolar epithelium between groups." (PMID 32984077, 2020). "The re-infection studies indicate Peli1 is involved in other steps of viral life cycle." (PMID 32544190, 2020). "The Peli1 deficiency profoundly promoted the induction of IFN-Is in microglia in response to stimulation by the ligands of TRIF-dependent TLRs, poly(I:C) and LPS, or infection by the RNA virus VSV." (PMID 26131354, 2015). "In this model we observed a significant increase in total neutrophils in Peli1−/− animals at 72 h post-instillation, and again saw higher levels of IL-6 and TNFα in BAL fluid at both 72 and 96 h post-infection." (PMID 32984077, 2020).
inflammation (3 papers, 2019 to 2025). Aberrant reaction of the microcirculation characterized by movement of fluid and leukocytes from the blood into extravascular tissues. "Both WT and Peli1−/− mice develop airway inflammation in acute and chronic airway inflammation models." (PMID 31417543, 2019).
neurological diseases (3 papers, 2019 to 2020). "Together, our findings established Peli1 as a critical regulator of microglial phagocytosis and highlighted the therapeutic potential by targeting Peli1 for the treatment of microglia-mediated neurological diseases." (PMID 33017390, 2020). "Therefore, targeting Peli1 may suppress expression of neurotoxins, and thus have therapeutic effect in neuroinflammation and related neurological diseases." (PMID 31142803, 2019).
cardiovascular disease (1 paper, 2025). "Recent research has shown that the PELI1 inflammasome promotes pyroptosis in cardiovascular disease." (PMID 40124544, 2025).
colorectal (1 paper, 2025). "For example, PELI1 activates the PI3 K/Akt/GSK3β signaling pathway, leading to poor prognosis of patients, and PELI3 promotes colorectal carcinogenesis through TLR4-mediated inflammation." (PMID 40500708, 2025).
PELI1 also shares sentences with these, for which no sentence is quoted: pancreatic cancer (3 papers); adenocarcinoma (2); chronic myeloid leukemia (2); colon cancer (2); Glucose intolerance (2); infectious disease (2); lymphoid tumors (2); neurodegenerative disease (2); ovarian failure (2); acute lung injury (1); acute myocardial infarction (1); atrial fibrillation (1); bacterial infections (1); bacterial myocarditis (1); Cerebral Edema (1); Cerebral ischemia (1); cervical adenocarcinoma (1); cervical squamous cancer (1); cholangiocarcinoma (1); colitis (1); colon polyps (1); colorectal adenocarcinoma (1); Crohn disease (1); Erythema (1); fibrosis (1); head and neck squamous cell carcinoma (1); Hyperkeratosis (1); Hypertension (1); hypertrophy (1); hypogammaglobulinemia (1).
A further 22 diseases each share a sentence with PELI1 in 1 paper.